LAMP1 (lysosome associated membrane protein 1)
Diseases named in the same sentence as LAMP1 in open-access papers (continued):
Sharing a sentence is not in itself a finding about the gene and the disease.
cancer (116 papers, 2009 to 2026). A tumor composed of atypical neoplastic, often pleomorphic cells that invade other tissues. "The high expression of LAMP1 in various human carcinomas suggests its utility as a versatile target for diagnostic and therapeutic oncology strategies." (PMID 40872517, 2025). "Through analysis, we observed a significant association between lower LAMP1 expression in cancer tissues (P=0.038) and higher T stage (P<0.001), M stages (P=0.003), clinical stages (P<0.001) as well as histologic grade (P=0.019)." (PMID 39669571, 2024). "Among other identified glycoproteins, lysosome-associated membrane glycoprotein 1 (LAMP1) has been reported to be a pro-invasive factor in cancer progression through abnormal localization on the plasma membrane of cancer cells." (PMID 35752862, 2022). "Taken together, these experiments further demonstrate that a constantly active mutant EGFR induces microtubule disorganization in cancer cells and causes LAMP1 mislocalization." (PMID 32194831, 2020). "To demonstrate the practical applicability of 3D super-resolution speckle microscopy to biological samples, we imaged lysosomes in fixed cultured HeLa cancer cells, immuno-labeled by targeting lysosomal associated membrane protein 1 (LAMP-1)." (PMID 30902978, 2019). "Lysosomal proteins are indeed good targets for cancer treatment, such as lysosome-associated membrane protein 1 (LAMP-1)." (PMID 28932704, 2017). "Notably, alterations in the glycosylation patterns of LAMP1 have been implicated in enhancing cancer cell adhesion to the endothelium and facilitating metastasis." (PMID 40872517, 2025). "Overexpression of LAMP1 is associated with numerous cancers and cancer metastasis." (PMID 38979135, 2025). "Confocal immunofluorescence microscopy images revealed the accumulation of lysosomes in the perinuclear space in cancer cells, which could be associated with marked changes in LAMP1 glycosylation, such as a decreased level of polylactosamine chains." (PMID 37250596, 2023). "This hypothesis was supported by studies showing implicated lysosomes in drug resistance phenotypes and LAMP-1 in cancer metastasis." (PMID 37768946, 2023). "This altered distribution of LAMP1 may serve as a useful surrogate for the presence of mutations across different cancer types." (PMID 32194831, 2020). "Furthermore, we found that BRD4 expression was negatively associated with both ATG5 and LAMP1 expression in pan-cancer patients, indicating that JQ1 increases the expression of ATG5 and LAMP1 via the suppression of BRD4 expression, subsequently inducing ferritinophagy." (PMID 30988278, 2019). "We interrogated public data from healthy and cancer tissues and observed a strong correlation of LAMP1 expression with other established senescence genes." (PMID 40545776, 2025). "In this study, we investigate the potential of LAMP1 as a novel imaging target in cancer diagnostics." (PMID 40872517, 2025). "The role of LAMP1 in regulating the interaction between the cancer cells and TME components is increasingly recognized in different epithelial cancers, which is vital for metastasis." (PMID 40872517, 2025). "Future studies incorporating comprehensive blocking experiments and expanded cancer models would strengthen the evidence for LAMP1-specific targeting and broaden the potential clinical applications of this imaging approach." (PMID 40872517, 2025). "Further investigations are warranted to assess LAMP1-based radiopharmaceuticals’ performance in the theranostic approach to these malignancies, especially for cancers with high mortality and limited therapeutic options." (PMID 40872517, 2025). "To evaluate LAMP1 abundance across various cancers, we quantified its expression using IF-based proteomics in matched human cancer and normal tissue samples, including prostate, breast, pancreas, colon, uterus, skin, kidney, and lymph nodes." (PMID 40872517, 2025).
cancer (continued). "This was further confirmed by studying the correlation of LAMP1 with several senescence phenotypes in healthy and cancer tissue samples, suggesting its involvement in the senescence cell fate." (PMID 40545776, 2025). "Expression of LAMP1 and LAMP2, the most abundant lysosomal membrane proteins, has been shown to be either upregulated or downregulated in cancer and associated with chemoresistance." (PMID 41381430, 2025). "Consistent with our findings, the omics data identified LAMP1 as a substrate of ST6GAL1, and α-2,6 sialylation of LAMP1 has been previously shown to promote cancer cell invasion and metastasis." (PMID 39937175, 2025). "In the last decades, several reports have shown that lysosomal membrane proteins, such as the lysosome-associated membrane proteins 1 and 2 (LAMP1 and LAMP2), are deregulated in different cancer types and their expression has been correlated to drug efficacy." (PMID 41381430, 2025). "This highlights the complex dynamics of the TME and underscores the potential of targeting LAMP1 as a theranostic strategy in cancer management." (PMID 40872517, 2025). "Next, Weston Blot was performed to detect the expression of LAMP1 protein in cancer tissues and adjacent tissues from 60 pairs of clinical ccRCC patients." (PMID 39669571, 2024). "Based on protein detection analysis, low expression of LAMP1 was observed in cancer tissues of 40 patients, whereas high expression of LAMP1 was detected in cancer tissues of the other 20 patients." (PMID 39669571, 2024). "LAMP1 expression was significantly lower in cancer tissues compared to paracancerous tissues(P<0.01)." (PMID 39669571, 2024). "Western blot analysis was employed to assess LAMP1 protein expression in cancer tissues and corresponding adjacent tissues from 60 pairs of ccRCC patients." (PMID 39669571, 2024). "Analysis of cancer and paracancer tissue samples from ccRCC patients demonstrated significantly lower levels of LAMP1 in tumors compared to paracancerous tissues (P<0.001), confirming its prognostic impact." (PMID 39669571, 2024). "Immunocytochemistry identified high levels of LAMP1 in the plasma membrane of cancer cells in human ccRCC and reduced levels of Zn, an indication that LE is a frequent event in ccRCC, potentially contributing to the loss of Zn." (PMID 37003503, 2023). "Analysis of human ccRCC revealed plasma membrane localization of LAMP1 on cancer cells, whereas kidney epithelial cells showed cytoplasmic localization." (PMID 37003503, 2023). "In A-498 and SNC-12 cells, P2XR4 colocalized with the main lysosomal protein, LAMP1, whereas it was expressed at lower levels in the 786–0 clear carcinoma cell line and in normal epithelial renal cells (HRE) then in A-498 and SNC-12 cells." (PMID 37231503, 2023). "Over-expressed LAMP1 also can influence cancer development inside the lysosomal membrane through increasing lysosomal exocytosis and lysosomal size." (PMID 35752862, 2022). "On the other hand, LAMP1 localization on the plasma membrane provided the binding ability to E-selectin through sialyl-LeX residues, thereby promoting the cancer cells adhering to extracellular matrix." (PMID 35752862, 2022). "It has been also proposed that LAMP1 facilitates the metastasis of cancers by acting as a ligand for galectin 3 and can increase translocation to the cell membrane." (PMID 35145930, 2022). "When we compared the epithelial expression levels of E-cadherin, LAMP1, and Giantin in all cancer cases pooled together compared to the control tissue, we recorded statistically significant differences (p = 0.011, p < 0.001, p = 0.037) in all three cases." (PMID 35203558, 2022).
cancer (continued). "Exploiting the low NEU1 > high lysosomal exocytosis axis, we developed a single-cell approach that relied on the increased levels of the Neu1 substrate Lamp1 at the PM of cancer and stromal cells." (PMID 36127469, 2022). "The preferential activation of CD4 T cells using antigen-LAMP1 fusion proteins has been shown previously in other cancers." (PMID 35651802, 2022). "Upregulation of LAMP1 expression has been reported to predict poor prognosis in various cancer subtypes including large B-cell lymphoma, epithelial ovarian cancer, breast cancer, and laryngeal squamous cell carcinoma." (PMID 33430230, 2021). "LAMP1 can significantly promote the development, proliferation, and metastasis of cancer, and the downregulation of LAMP1 can inhibit the metastasis of cancer." (PMID 31799198, 2019). "LAMP1 can be overexpressed at the surface of cancer cells while its location is usually to the endosome-lysosomal membrane in normal cells with sometimes a low amount (1–2%) at the membrane." (PMID 29409507, 2018). "Cell surface expression of LAMP1 can serve as a ligand for selectins and help mediate cell-cell adhesion correlating with increased cancer invasiveness." (PMID 29137220, 2017). "LAMP-1 is suggested to have a role in cell–cell adhesion and migration, since it was detected on the surface of highly metastatic cancer cells, particularly from colon cancer." (PMID 28932704, 2017). "For example, in carcinoma cells, relevant glycoprotein ligands of galectin-1 were identified as lamp-1 and lamp-2, carcinoembryonic antigen, and the fibronectin receptor." (PMID 19898636, 2009). "Moreover, LAMP1 expression strongly correlated with p21 in cancer tissue (R = 0.95) and with the surface senescence marker PLAUR (uPAR), which has also been reported as a SEN surface marker and target for senolytic immunotherapy." (PMID 40545776, 2025). "In the last decades, several reports have shown that lysosomal membrane proteins, particularly lysosome-associated membrane proteins (LAMPs) 1 and 2 (LAMP1 and LAMP2), are deregulated in different cancer types and their expression has been associated with drug resistance." (PMID 41381430, 2025). "Interestingly, in this study, by leveraging integrated single-cell and spatially resolved RNA sequencing, we demonstrated that in the TME, besides the cancer cells, MDSCs and CAFs are the primary sources of LAMP1 expression." (PMID 40872517, 2025). "Additionally, through pan-cancer bioinformatic analysis, we observed a high abundance of LAMP1 across various cancer types." (PMID 40872517, 2025). "This variability in uptake across different cancer models suggests that the clinical translation of LAMP1-targeted imaging may require optimization for specific cancer subtypes." (PMID 40872517, 2025). "Additionally, xenograft models showed a significantly higher contribution of cancer cells than the immune cells to cell surface LAMP1 expression." (PMID 40872517, 2025). "Furthermore, cisplatin-resistant cancer cells are characterized by reduction in the lysosomal compartment with downregulation of LAMP-1 and LAMP-2." (PMID 40277899, 2025). "Notably, upregulation of LAMP1 on the cell surface correlates with enhanced cancer cell adhesion, migration, and metastasis across multiple adenocarcinomas, including those of the colon, breast, and pancreas." (PMID 40872517, 2025). "Given that cancer cells, MDSCs, and CAFs are the main sources of LAMP1 expression, we sought to determine whether LAMP1 expression correlates with the anatomical location of tumoral cells." (PMID 40872517, 2025). "Indeed, downregulation of LAMP-1 has been previously shown to sensitize cells to lysosomal mediated death pathways while increased levels of LAMP-1 mRNAs was observed in various human cancers." (PMID 37768946, 2023). "Moreover, the percentage of CD47 colocalized with LAMP1 decreased in A549, H1299 cancer cells compared to that in HBE normal cells." (PMID 36823443, 2023).
cancer (continued). "Cancer cells were live stained with an anti-LAMP-1 antibody 5 min after FSS treatment for 30 min." (PMID 33526716, 2021). "We looked to see if the diffuse cytoplasmic distribution of LAMP1 may also apply to these other cancer types." (PMID 32194831, 2020). "Many reports show that LAMP1 and LAMP2 are implicated in promoting cancer progression." (PMID 31425520, 2019). "LAMP1 is upregulated in many types of cancer, including colorectal adenocarcinoma." (PMID 30344951, 2018). "Some proteins, such as Vimentin (VIM), Rho GDP-dissociation inhibitor 1 (Rho GDI), Lysosome-associated membrane glycoprotein 1 (LAMP1) and Membrane-associated progesterone receptor component 2 (PGRMC 2), have been previously identified as potential biomarkers for various cancers." (PMID 25477298, 2014). "Two homologs of LAMP3, LAMP1 and LAMP2, have been associated with cancer metastasis previously." (PMID 23294542, 2013). "LAMP1 is typically localized on lysosomal membranes, but it can also be transiently displayed on the cell surface under certain conditions, which is of particular interest in immunology and cancer research due to its role in cell signaling, migration, and immune modulation." (PMID 40545776, 2025). "In addition, LAMP1, ATIC was also associated with various cancers in a autophagy‐dependent manner." (PMID 33837652, 2021). "However, we found miR‐615‐5p could not interacted with circ‐LAMP1 in our study, suggesting the tissue specific mechanism of circ‐LAMP1 in human cancers." (PMID 33675150, 2021). "LAMP1, LAMP2, and LAMP3 are the key LAMP isoforms emerging as important potential players in cancer biology." (PMID 33430230, 2021). "Treatment with NMTi also led to the accumulation of LAMP1-positive vesicles in H1792, as well as in HCT116, A375, HeLa and SKOV3 cancer cells." (PMID 32686708, 2020). "LAMP1 and LAMP2 were expressed in the cytoplasm of cancer cells and inflammatory cells, whereas CDHR2 was only expressed in the cytoplasm of cancer cells." (PMID 31425520, 2019). "For LAMP1 and LAMP2 it has been previously established that their expression can relocalize to the plasma membrane in cancer cells." (PMID 23294542, 2013). "Notably, various lysosome specific proteins (LAMP-1/5) and enzymes (CTSB/D/F/G/S/W) were also found to be expressed significantly lower in FA SCC cancers." (PMID 41188232, 2025). "Among them, LAMP1, LAMP2, LAMP4 and LAMP5 have been studied in relation to cancer and immunity." (PMID 38146591, 2024). "Additionally, CHI3L1 overexpression promoted the formation of autophagosomes in various cancer cell lines: it also increased the co-localization of LC3 and the lysosome marker protein LAMP-1, indicating an increase in the production of autolysosomes." (PMID 37340009, 2023). "Interestingly, we found CD47 partially colocalized with LAMP1, a lysosome marker, in all of HBE normal epithelial cells and A549, H1299 cancer cells." (PMID 36823443, 2023). "Knockdown of LAMP1 reversed the UBL4A-induced autophagy suppression, mesenchymal-to-epithelial transition, inhibiton of autophagic flux, inhibition of cancer cell migration and invasion, cell proliferation and wound healing capacity." (PMID 31288830, 2019). "Western blot analysis showed that little exosomal Survivin was detectable in plasma samples collected from six controls having no previous diagnosis of cancer in comparison to the exosome-specific protein Lamp1." (PMID 23091600, 2012). "The spatial distribution of lysosomes is involved in cancer cell metastasis and drug resistance.38,39) These irregular lysosomal distributions may not be independent of the remarkable changes in LAMP1 glycosylation." (PMID 37250596, 2023).
neurodegenerative disease (10 papers, 2013 to 2024). A disorder of the central nervous system characterized by gradual and progressive loss of neural tissue and neurologic function. "Axonal spheroids are also known to contain the abnormal accumulation of organelles and vesicles in several degenerative diseases and their enlargement is caused by the accumulation of aberrantly enlarged LAMP1-positive endo-lysosomal vesicles." (PMID 37667395, 2023). "LAMP1 has been recently studied as a potential candidate marker of lysosomal alteration in neurodegenerative diseases with decreases shown in CSF in PD, although it has been previously reported to be unaltered in FTD." (PMID 37917233, 2024). "However, they didn’t find evidence to support the LAMP1/2 as the specific markers to assess lysosome distribution in neurodegenerative diseases, which requires additional studies to confirm in the future." (PMID 35873477, 2022). "Some researchers have observed a decrease in the co-localization of LAMP1 and LC3 in neurodegenerative diseases with lysosomal malfunction." (PMID 24143204, 2013). "The lack of hyperglycosylated LAMP1 in affected CNS tissues from other mouse models of neurodegenerative diseases that exhibit neuro-inflammation renders our observation specific to NPC, suggesting a unique function associated with this protein in the context of NPC." (PMID 31999726, 2020).
infectious disease (4 papers, 2015 to 2023). A disorder directly resulting from the presence and activity of a microbial, viral, or parasitic agent in humans. "The presence of lysosomal-associated membrane protein-1 (LAMP-1 or CD107a) on the surface of cytolytic cells characterizes the process of cell degranulation and the effector immune response in infectious diseases." (PMID 36839443, 2023).
neurological diseases (4 papers, 2009 to 2023). "Improper LAMP-1 localization has also been observed in other neurological diseases." (PMID 36755323, 2023).
bacterial infection (2 papers, 2021). "After bacterial infection of the MDMs, we performed kinetics at different processing times of 30, 60, and 120 min, and detected Rab 5 (red) and Lamp-1 (yellow) by confocal microscopy." (PMID 34944407, 2021).
kidney disease (2 papers, 2021 to 2025). "In summary, our study revealed an increase in neutrophilic surface and soluble LAMP1 in SLE, especially in patients with proliferative LN, with potential as a noninvasive biomarker of kidney disease." (PMID 40760840, 2025).
vasculopathy (2 papers, 2014 to 2018). "Thus, tissue-specific variability in relative LAMP protein abundance may modulate the vascular phenotypes; the tissues in which alternate LAMP-1 upregulation can not compensate for the defective LAMP-2 in VMSC are more susceptible to injury leading to vasculopathy." (PMID 29463847, 2018).
adenocarcinoma (1 paper, 2025). A common cancer characterized by the presence of malignant glandular cells. "To further characterize LAMP1 expression patterns, we employed cell-based flow cytometry analysis across five distinct adenocarcinoma cell lines: breast (MDA-MB-231), lung (KL205), colon (Caco-2), and pancreatic (SU86 and CAPAN2)." (PMID 40872517, 2025). "LAMP-1 imaging can be expanded to adenocarcinomas of other origins, such as prostate and pancreas." (PMID 40872517, 2025).
LAMP1 also shares sentences with these, for which no sentence is quoted: myeloma (10 papers); liver fibrosis (7); parasitemia (4); allergies (3); autoimmune disease (3); bladder tumor (3); cutaneous leishmaniasis (3); erythroleukemia (3); Gaucher disease (3); lung adenocarcinoma (3); metastatic tumor (3); multiple myeloma (3); pertussis (3); preeclampsia (3); acute lymphoblastic leukemia (2); AIDS (2); B-cell lymphoma (2); cholangiocarcinoma (2); chronic myelogenous leukemia (2); colorectal neoplasm (2); Dengue hemorrhagic fever (2); dyslipidemia (2); endometriosis (2); hemophagocytic lymphohistiocytosis (2); inflammation (2); Listeria monocytogenes infection (2); lymphopenia (2); Splenomegaly (2); Thrombocytopenia (2); abortion (1).
A further 101 diseases each share a sentence with LAMP1 in 1 paper.